PTGES (prostaglandin E synthase)
Diseases named in the same sentence as PTGES in open-access papers (continued):
Sharing a sentence is not in itself a finding about the gene and the disease.
pancreatic cancer (5 papers, 2018 to 2025). "In summary, our study established an association of PTGES expression with pancreatic cancer metabolism and the immune microenvironment." (PMID 37108468, 2023). "Based on tissue expression and survival analysis, only the PTGES gene was significantly increased in pancreatic cancer patients and associated with worse prognosis of patients." (PMID 37108468, 2023). "Our data here identify a link between higher mutational burden in key driver genes for pancreatic cancer and PTGES expression." (PMID 37108468, 2023). "In summary, our data indicated that PTGES has an oncogenic function and is associated with poor prognosis in pancreatic cancer patients." (PMID 37108468, 2023). "Among all cancer types, PTGES is prominently associated with worse prognosis in pancreatic cancer." (PMID 37108468, 2023). "Importantly, PTGES expression associates better with poor prognosis of pancreatic cancers and patient survival in an immune-deficient microenvironment." (PMID 37108468, 2023). "Pancreatic cancer patients with high PTGES expression correlated with a high mutational burden." (PMID 37108468, 2023). "Database analysis has reported higher expression of PTGES in pancreatic tumors than in normal pancreatic tissues." (PMID 40318167, 2025). "PTGES protein expression was found to be significantly higher in pancreatic tumor sections compared to normal pancreatic tissue sections." (PMID 37108468, 2023). "While the functional role of prostaglandin E2 metabolite has been extensively studied, there is a limited understanding of the PTGES enzyme in pancreatic cancer." (PMID 37108468, 2023). "To explore the role of PTGES in mediating oncogenic signaling in pancreatic cancer, we analyzed differentially expressed genes between PTGESHigh and PTGESLow patient groups." (PMID 37108468, 2023). "Although the PTGES gene was shown to be oncogenic in multiple cancers, only pancreatic cancer had a significant q-value Cox coefficient." (PMID 37108468, 2023). "Our analysis identified higher expression of PTGES in pancreatic tumors compared to normal pancreatic tissues, suggesting an oncogenic function." (PMID 37108468, 2023). "Further, the mRNA expression of all the three PTGES isoforms was significantly increased in pancreatic cancer tissues from The Cancer Genome Atlas (TCGA) study, compared to the normal pancreatic tissues from the GTEx study." (PMID 37108468, 2023). "Here, we investigated the relationship between expression of prostaglandin E synthase (PTGES) isoforms and the pathogenesis and regulation of pancreatic cancer." (PMID 37108468, 2023). "In this study, we evaluated the prognostic significance and function of PGE2 synthesizing PTGES isoforms in regulating multiple aspects of pancreatic cancer progression using meta-analysis of publicly available datasets." (PMID 37108468, 2023). "PTGES expression is specifically increased in pancreatic tumor tissues compared to normal pancreatic tissue." (PMID 37108468, 2023). "Further, we investigated how PTGES expression influences the prognostic outcomes in overall survival of pancreatic cancer patients in multiple immune cells with enriched or depleted microenvironments." (PMID 37108468, 2023). "We further checked whether the PTGES genes were correlated with disease-free survival of pancreatic cancer patients." (PMID 37108468, 2023). "Thus, our study here provided valuable insights into the plausible mechanism of PTGES-mediated oncogenic effects in pancreatic cancer." (PMID 37108468, 2023). "Recently, PTGES was identified as a candidate gene in a proteogenomic screen for pancreatic cancer." (PMID 37108468, 2023). "We therefore emphasized finding the significance of the PTGES gene in pancreatic cancer." (PMID 37108468, 2023). "Since PTGES expression was higher in pancreatic cancer tissues, we next evaluated whether any of the PTGES isoforms could predict the prognosis of pancreatic cancer patients." (PMID 37108468, 2023).
pancreatic cancer (continued). "However, another study comprising a larger patient cohort showed only the PTGES isoform to be significantly increased in pancreatic cancer tissues compared to normal pancreatic tissues." (PMID 37108468, 2023). "Overall, our data here propose that PTGES could be a key regulator of metabolic and immune pathways in pancreatic cancer." (PMID 37108468, 2023). "We noted higher PTGES protein expression in multiple pancreatic tumor sections." (PMID 37108468, 2023). "To summarize, our comprehensive study identified that PTGES could be a major regulator of oncogenic signaling and a prognostic marker for pancreatic cancer patients." (PMID 37108468, 2023). "The findings also show that ALDH3B1, PTGES, and TUFT1, the downstream genes of ZIC5, contribute to gemcitabine resistance in pancreatic cancer cells." (PMID 40318167, 2025). "A mechanism involving microsomal prostaglandin E synthase-1 (mPGES-1) and 5-lipoxygenase (5-LOX) is proposed by iNKT cells to inhibit M2 TAMs in the pancreatic cancer model." (PMID 40422244, 2025). "In another study utilizing single-cell sequencing data of pancreatic cancer, PTGES3 expression was prominently seen in multiple immune cells, whereas PTGES expression was mostly confined to fibroblast and tumor cells." (PMID 37108468, 2023).
bladder cancer (4 papers, 2019 to 2020). "In mouse bladder cancers, PD-L1 expression on tumor-associated myeloid cells is associated with the expression of cyclooxygenase-2 (COX2), microsomal prostaglandin E synthase-1 (mPGES1), prostaglandin E2 (PGE2) and the capacity to induce apoptosis of CD8+ T cells." (PMID 31130949, 2019).
COVID-19 (4 papers, 2021 to 2025). A disease caused by infection with severe acute respiratory syndrome coronavirus 2. "Similarly, COX-1, COX-2, and PTGES were upregulated in peripheral blood mononuclear cells isolated from patients with COVID-19 compared with healthy controls." (PMID 38807598, 2024). "Moreover, cox-1, cox-2, and PTGES have been shown to be upregulated in peripheral blood mononuclear cells isolated from patients with COVID-19 compared with healthy controls." (PMID 37047078, 2023). "Inhibition of the microsomal prostaglandin E synthase-1 (mPGES-1) by sonlicromanol (Khondrion; a drug currently in phase 2b studies for mitochondrial disease), may also be beneficial in COVID-19 patients." (PMID 34347801, 2021).
epithelial ovarian cancer (4 papers, 2006 to 2023). "It was reported that noradrenaline could activate β2-ARs and transcriptionally activate PTGS-2 and PTGES via nuclear factor-kappaB (NF-kappaB) to produce PGE2 in human ovarian cancer cells." (PMID 36982930, 2023). "Noradrenaline increased the PTGS-2 and PTGES mRNA/protein expression and the PGE2 release from human ovarian cancer cells and PTGS-2 mRNA/protein expression and PGE2 secretion from lipopolysaccharide (LPS)-induced rat primary microglia." (PMID 36982930, 2023). "Literature data describing the receptor mechanisms of adrenergic stimulation in PGE2 synthesis/secretion during pathological states show that the activation of β2-ARs increased the PTGE-2 and PTGES expression and PGE2 release from human ovarian cancer cells." (PMID 36982930, 2023).
viral infection (4 papers, 2014 to 2024). "Also, the ex vivo infection of living human PCLS with SARS-CoV-2 (viral infection analyzed by NSP7 qRT-PCR) led to an upregulation of COX-2 expression compared with non-infected control slices, while HPGD mRNA levels were unchanged and PGE synthase (PTGES) expression tended to be increased." (PMID 34347801, 2021).
adenoma (3 papers, 2006 to 2021). A neoplasm arising from the epithelium. "The authors also found seven markers specifically able to differentiate between large adenomas and CRC (BCL3, PTGES, PPARG, MMP11, IL8, TNFSF13B, CXCR3)." (PMID 33806465, 2021).
asthma (3 papers, 2018 to 2024). "Recently, the eMERGE (electronic medical records and genomics) network conducted an asthma GWAS in biobank subjects, and reported one genome-wide significant association in African Americans, SNP rs11788591, intronic to the PTGES gene." (PMID 30787307, 2019).
cerebral aneurysm (3 papers, 2013 to 2020). "Membrane-associated prostaglandin E synthase (mPEGS)-1 plays a protective role in blood vessels, and aspirin was shown to attenuate cerebral aneurysm rupture and reduce mortality in a mouse mPGES-1 deficiency model of IA." (PMID 32546267, 2020).
pulmonary fibrosis (3 papers, 2014 to 2024). Chronic progressive interstitial lung disorder characterized by the replacement of the lung tissue by connective tissue, leading to progressive dyspnea, respiratory failure, or right heart failure. "Taken together, our data suggest that PTGES is a propitious fibrosis therapeutic target and a novel biomarker in lung fibrosis." (PMID 39417702, 2024). "Deficiency in microsomal prostaglandin E synthase-1 (mPGES-1), the enzyme that converts prostaglandin H2 (PGH2) to PGE2 worsens bleomycin induced pulmonary fibrosis." (PMID 26248335, 2015). "Hence, we observed PTGES, a lipid metabolic enzyme, to elucidate the interplay between PTGES and lung fibrosis development and progression." (PMID 39417702, 2024). "Next, we evaluated PTGES expression levels in the case of lung fibrosis in rats." (PMID 39417702, 2024). "Furthermore, PTGES was upregulated in a lung fibrosis rat model in vivo." (PMID 39417702, 2024).
cognitive decline (2 papers, 2019 to 2025). "Some of these genes are also involved in aging, and prostaglandin E synthase (PTGES3), an enzyme involved in prostaglandin‐2 synthesis, has been shown to be upregulated in aging‐induced cognitive decline." (PMID 39380362, 2025).
colorectal tumors (2 papers, 2015 to 2023). "We studied the PG-pathway in gene expression databases and we found that PTGS2 (prostaglandin G/H synthase and cyclooxygenase) and PTGES (prostaglandin E synthase) are co-expressed in human colorectal tumors." (PMID 26498686, 2015). "Regarding colorectal tumors PTGS2, PTGES and PTGER3 were found up-regulated in many datasets." (PMID 26498686, 2015). "PTGS2 and PTGES are both up-regulated in colorectal tumors when compared to normal tissue, while the PG receptor genes expression levels vary considerably, not correlating with the expression of PTGS2 and PTGES (not shown)." (PMID 26498686, 2015).
epilepsy (2 papers, 2021 to 2022). A brain disorder characterized by episodes of abnormally increased neuronal discharge resulting in transient episodes of sensory or motor neurological dysfunction, or psychic dysfunction. "In animal models, neuroinflammation, associated with the release of proinflammatory cytokines and other mediators, including cyclooxygenase and prostaglandin E synthase enzymes, has been shown to be involved in neurological disorders, including seizure and epilepsy." (PMID 32986132, 2022).
Fever (2 papers, 2018 to 2021). Body temperature elevated above the normal range. "LPS-induced fever is absent in mice deficient in microsomal prostaglandin E synthase-1 (mPGES-1), which lack PGE2 synthesis, suggesting that fever is mediated by PGE2." (PMID 34276287, 2021).
gastritis (2 papers, 2021 to 2022). Inflammation of the stomach. "By playing a role in inflammatory responses, fever and pain, PTGES protein has been reported to be involved in inflammatory diseases such as collagen-induced arthritis and gastritis." (PMID 35562597, 2022).
myotonic dystrophy type 1 (2 papers, 2016 to 2025). Steinert disease, also known as myotonic dystrophy type 1, is a muscle disease characterized by myotonia and by multiorgan damage that combines various degrees of muscle weakness, arrhythmia and/or cardiac conduction disorders, cataract, endocrine damage, sleep disorders and baldness. "In myotonic dystrophy type 1 (DM1), PGE2 was found to be increased through the up-regulation of Cox2, microsomal prostaglandin E synthase-1 (mPGES-1), and prostaglandin EP2/EP4 receptors." (PMID 39851544, 2025).
nasal polyps (2 papers, 2020 to 2024). "First, we performed reverse transcription-quantitative polymerase chain reaction (RT-qPCR) to examine the mRNA expression levels of mPGES-1 (encoded by PTGES) and PGE2 receptors (EP1–4, encoded by PTGER1–4) in the nasal polyps of ECRS or non-ECRS patients." (PMID 39015572, 2024). "In humans, PTGES expression is lower in the nasal polyps of individuals with chronic sinusitis than in those with normal nasal mucosa." (PMID 39015572, 2024).
acne (1 paper, 2020). An inflammatory process of the sebaceous glands which is characterized by comedones, nodules, papules and/or pustules on the skin. "Based on microarray datasets GSE10432, GSE10433, and GSE11792, upregulated expression of LCN2, PTGES, and GDF15 might mediate sebocytes apoptosis; CCL2 and S100A7 could be related with “acne-flare” using isotretinoin for 1 week." (PMID 32685503, 2020). "Using isotretinoin for 1 week, LCN2, PTGES, and GDF15 were upregulated and might mediate sebocytes apoptosis and thus decreased sebum production; CCL2 originated from activated TNF signaling pathway and S100A7 could be related with “acne-flare”." (PMID 32685503, 2020). "In conclusion, this study exhibits that the upregulated expression of LCN2, PTGES, and GDF15 might mediate sebocytes apoptosis and thus decreased sebum production; while CCL2 originated from activated TNF signaling pathway and S100A7 could be related with “acne-flare” using isotretinoin for 1 week." (PMID 32685503, 2020).
bone cancer (1 paper, 2022). A primary or metastatic malignant neoplasm affecting the bone or articular cartilage. "PTGES can promote bone cancer growth and bone cancer pain in mice." (PMID 35664305, 2022).
brain cancer (1 paper, 2020). A primary or metastatic malignant neoplasm affecting the brain. "Additionally, several reports associate the overexpression of enzymes such as Ciclooxigenase-2 (COX-2), prostaglandin E synthase (PGES), and Cytochrome P450 Family 2 and 4 (CYP2s and CYP4s) with the development of different types of brain cancer." (PMID 32560280, 2020).
colon adenoma (1 paper, 2023). An adenoma that arises from the colon. "Prostaglandins E2 (PGE2) produced by PTGS2 and PTGES has been reported to have a vital role in CRC tumorigensis and celecoxib, a selective inhibitor of PTGS2, reduced colon adenoma in ApcMin/+ mice by blocking PGE2 synthesis." (PMID 37041160, 2023).
colonic adenomatous polyps (1 paper, 2021). "PTGES is upregulated in CRC and premalignant lesions such as colonic adenomatous polyps." (PMID 33670198, 2021).
disc degeneration (1 paper, 2022). "Chondrocytes 2 expressing MGP, MT1G, and GPX3 may play a role in reversing calcification and degeneration, and chondrocytes 4 expressing PTGES, TREM1, and TIMP1 may play a role in disc degeneration pain and inflammation." (PMID 35874809, 2022).
endometrial adenocarcinomas (1 paper, 2011). "Here, we undertook a comprehensive analysis of the expression profile of the PGE synthase enzymes (PTGES, -2, -3) and E-series prostanoid receptors (PTGER1–4) in endometrial adenocarcinoma by quantitative RT-PCR analysis." (PMID 21589857, 2011). "Here we investigated (a) the expression profile of the PGE synthase enzymes (PTGES, PTGES-2, PTGES-3) and PGE receptors (PTGER1–4) in endometrial adenocarcinomas compared with normal endometrium and (b) the role of PTGER4 in endometrial tumorigenesis in vivo." (PMID 21589857, 2011).
esophageal cancer (1 paper, 2023). A primary or metastatic malignant neoplasm involving the esophagus. "Previously, PTGES was shown to be an HIF-inducible gene in esophageal cancer." (PMID 37108468, 2023).
glaucoma (1 paper, 2021). Increased pressure in the eyeball due to obstruction of the outflow of aqueous humor. "The down-regulated of PTGES was also found in gene expression level compared glaucoma samples to normal samples." (PMID 33946922, 2021).
hyperglycaemia (1 paper, 2023). "Remarkably, Ptgs2/Cox2-induced expression and PGE2 production in islet beta cells was shown to promote hyperglycaemia in vivo, in transgenic mice overexpressing Ptgs2/Cox2 and Prostaglandin E Synthase (Pges) in beta cells under the rat insulin promoter (RIP)." (PMID 37705740, 2023).
leukemia (1 paper, 2021). A malignant (clonal) hematologic disorder, involving hematopoietic stem cells and characterized by the presence of primitive or atypical myeloid or lymphoid cells in the bone marrow and the blood. "Despite the initial observation of upregulated PGE2 pathway components in murine leukemia, we could not associate prognostic value to PTGS, PTGES, and PTGER in human AML." (PMID 34502319, 2021).
lumbar disc degeneration (1 paper, 2024). "Some genes are widespread in chondrocyte 4, and chondrocyte 5 may play an important role in the process of lumbar disc degeneration together with the Wnt/Ca2+signaling pathway, such as ANGPTL4, PTGES, IGFBP3, GDF15, TRIB3, and TNFRSF10B." (PMID 38654287, 2024). "ANGPTL4, IGFBP3, PTGES in chondrocytes 4 and TRIB3, GDF15, TNFRSF10B in chondrocytes 5 may play an important role in the lumbar disc degeneration process." (PMID 38654287, 2024).
nephrosclerosis (1 paper, 2023). Hardening of the kidney due to infiltration by fibrous connective tissue (fibrosis), usually caused by renovascular diseases or chronic hypertension. "We aimed to determine whether genetic variability represented by 38 tag-SNPs in genes of the cyclooxygenase pathway (PTGS1, PTGS2, PTGES, PTGES2 and PTGES3) leading to prostaglandin E2 (PGE2) synthesis, modified CV traits and events in 493 nephrosclerosis patients." (PMID 36690661, 2023).
osteosarcoma (1 paper, 2023). A usually aggressive malignant bone-forming mesenchymal neoplasm, predominantly affecting adolescents and young adults. "FUBP1 binds to and promotes PTGES promoter activity and sustains the AA metabolism pathway in osteosarcoma cells." (PMID 37180822, 2023). "We found that the expression level of FUBP1 in the clinical osteosarcoma samples was positively correlated with the expression level of PTGES and CYP2C19 (p = 0.002, and p = 0.005)." (PMID 37180822, 2023). "In the present study, we found that FUBP1 transcriptionally promotes the expression of PTGES and sustains the activation of the AA pathway in lobaplatin‐treatment osteosarcoma cells." (PMID 37180822, 2023). "We also found that the upregulation of PTGES significantly decreased the sensitivity of osteosarcoma cells to lobaplatin due to interference with FUBP1." (PMID 37180822, 2023). "Our findings provide evidence that FUBP1 plays a critical role in the process of lobaplatin resistance in human osteosarcoma through the transcriptional regulation of PTGES and activation of AA metabolism." (PMID 37180822, 2023). "The necessity of PTGES activation to allow FUBP1 to enhance resistance to chemotherapy in osteosarcoma cells was further investigated." (PMID 37180822, 2023). "Targeting FUBP1, its downstream target PTGES and the AA metabolic pathway may be promising strategies for sensitizing chemoresistant osteosarcoma cells to lobaplatin." (PMID 37180822, 2023). "Taken together, these results indicate that knockdown of PTGES could sensitize osteosarcoma cells to lobaplatin." (PMID 37180822, 2023). "In addition, our study showed that PTGES inhibition enhances the sensitivity of osteosarcoma cells to lobaplatin, which leads to the suppression of tumor cells." (PMID 37180822, 2023). "The clinical relevance of FUBP1 expression in terms of the activation of PTGES and CYP2C19 (a key CYP epoxygenase enzyme in AA metabolism) was further investigated in a group of human osteosarcoma clinical specimens using IHC analysis." (PMID 37180822, 2023). "The selective PTGES inhibitor CAY10526 and agonist of EP2 receptor Evatanepag, which are crucial elements in AA metabolic pathway, were also used, and the chemosensitivity of osteosarcoma cells to lobaplatin was markedly reduced and elevated, respectively." (PMID 37180822, 2023).